TF (transferrin)
Diseases named in the same sentence as TF in open-access papers (continued):
Sharing a sentence is not in itself a finding about the gene and the disease.
colorectal cancer (36 papers, 2007 to 2026). A primary or metastatic malignant neoplasm that affects the colon or rectum. "KRAS mutations have also been associated with increased TF expression levels in colorectal cancer and NSCLC." (PMID 33996610, 2021). "This study investigated whether preoperative serum transferrin, a rapid‐turnover protein, was associated with prognosis after colorectal cancer (CRC) resection." (PMID 33860145, 2021). "As early as 1978, research teams began exploring the significance of prealbumin, retinol-binding protein, transferrin, and albumin levels in colorectal cancer patients." (PMID 41450918, 2025). "The prognostic value of transferrin has been observed in upper gastrointestinal and colorectal cancer." (PMID 38438901, 2024). "Low transferrin levels were confirmed as a prognostic predictor in patients with upper gastrointestinal cancer and colorectal cancer." (PMID 38438901, 2024). "For instance, HNF4A, a well-established gastrointestinal-specific transcription factor, ranked as the second most enriched TF in colorectal cancer-specific CREs." (PMID 38213995, 2024). "The regulatory mechanism of TF expression has been reported in many cancer models containing brain, breast, and colorectal cancer." (PMID 37940761, 2024). "The human colorectal cancer (CRC) cell line HROC173 was treated with 5-FU or gemcitabine to stimulate TF expression." (PMID 38719932, 2024). "For colon and colorectal cancer, mixed findings were observed with serum ferritin, iron, and transferrin saturation." (PMID 39246326, 2024). "We investigated the cytotoxicity of hRTL against DLD-1, human colorectal carcinoma cells that are known to highly express the TF-antigen." (PMID 39330281, 2024). "Previous studies have reported that cell-free DNA promoter profiling and TF profiling is capable of prediction of tumor subtypes in prostate and detect early-stage colorectal cancer." (PMID 36463222, 2022). "This study’s objective was to analyze the abnormalities in TF expression, their impact on patient prognosis, and related pathways in colorectal cancer (CRC)." (PMID 36344988, 2022). "ROS levels and transferrin expression were elevated in RSL3-treated colorectal cancer cells, while GPX4 expression was reduced." (PMID 36192693, 2022). "The same colorectal cancer in vitro model was employed to reveal the cytotoxic and proapoptotic effects of 5-FU loaded transferrin liposomes." (PMID 34066710, 2021). "The same mechanism has been described in the activation of TF expression in breast and colorectal carcinoma cells." (PMID 31467489, 2019). "Reduced TF expression can decrease cancer cell growth, and selective reduction of TF expression with mRNAi in colorectal cancer cells reduced tumor growth in mice." (PMID 27083051, 2016). "In a nested case–control study carried out within a cohort of New York women, no overall associations were seen for levels of serum iron, ferritin, TIBC, transferrin saturation, or for iron intake (diet+supplements) with colorectal cancer." (PMID 17551493, 2007). "Among them, three TF genes, E2F1, E2F3, and BRCA1, were validated as differentially expressed in databases of psoriasis and colorectal cancer, confirming their designation as hub TFs." (PMID 39045407, 2024).
colorectal cancer (continued). "The expression of TF epitope, detected by histochemistry with PNA lectin, was evaluated in 96 colorectal carcinomas and detected in 55 cases (57%)." (PMID 33572915, 2021). "While the abundance of TFR1 impacts colorectal cancer cell proliferation rates, this is particularity appealing for engineering nanoparticles in CRC-targeted therapy by surface functionalization with TFR’s natural ligand transferrin." (PMID 34066710, 2021). "In patients with colorectal cancer, the sIL-2R level was significantly correlated with neutrophil count (P < 0.01, r = 0.501) and MDSC level (P < 0.05, r = 0.453) and inversely correlated to lymphocyte count (P < 0.05, r = -0.472) and transferrin level (P < 0.0005, r = -0.614)." (PMID 29147299, 2012).
heart failure (36 papers, 2010 to 2025). Inability of the heart to pump blood at an adequate rate to meet tissue metabolic requirements. "Ferritin <30 ng/ml was associated with the long-term outcome of both the general and heart failure populations, while transferrin saturation (TSAT) <20% was associated with the 5-year mortality of heart failure patients and the relatively healthy population aged 45 years and above." (PMID 38562191, 2024). "The diagnostic landscape presents both challenges and opportunities, where traditional markers like ferritin and transferrin saturation require careful interpretation against the backdrop of heart failure’s inflammatory milieu." (PMID 40363966, 2025). "The diagnostic differentiation emphasizes the inadequacies of depending just on serum ferritin for evaluating iron status in heart failure, highlighting the necessity for a comprehensive examination utilizing both ferritin and transferrin saturation (TSAT)." (PMID 40363966, 2025). "Patients with heart failure, left ventricular ejection fraction ≤45%, and either transferrin saturation <20% or serum ferritin <100 μg/L were enrolled." (PMID 39443013, 2024). "In the IRONMAN trial, 1137 patients with heart failure, ejection fraction ≤ 45%, and either serum ferritin < 100 μg/L or transferrin saturation (TSAT) < 20% were randomized to intravenous ferric derisomaltose (FDI) or usual care." (PMID 38446126, 2024). "Limited data are available regarding the association between serum transferrin saturation (TSAT) levels and heart failure (HF)." (PMID 39280001, 2024). "Based on previous studies, in patients with heart failure, ID has been defined as the presence of either a serum ferritin concentration <100 μg/L or 100–299 μg/L if the transferrin saturation (T-sat) is <20%." (PMID 36363528, 2022). "Ferritin levels of < 100 μg/L or < 300 μg/L and low transferrin saturation (TSAT) of <20% have been used to diagnose heart failure patients with both absolute and functional ID." (PMID 36017290, 2022). "Previous studies have reported that RDW correlated negatively with markers of nutrition, such as albumin, prealbumin, transferrin, and total cholesterol levels, in heart failure patients and in PD patients." (PMID 25961836, 2015). "The three primary endpoints were (i) time to cardiovascular death or first heart failure hospitalization, (ii) total heart failure hospitalizations, and (iii) time‐to‐first event of cardiovascular death or heart failure hospitalization only in patients with transferrin saturation <20% at baseline." (PMID 40740027, 2025). "Some studies have reported greater increases in ferritin and transferrin saturation in heart failure with preserved ejection fraction (HFpEF) patients compared to HFrEF, with no comparable improvements in ejection fraction, yet no clear impact on rehospitalization rates." (PMID 40896039, 2025). "The third primary endpoint of time‐to‐first cardiovascular death or heart failure hospitalization in patients with transferrin saturation <20% occurred in 81 men in the treatment group compared with 113 in the placebo group (HR 0.73; 95% CI 0.55–0.97, p = 0.028)." (PMID 40740027, 2025). "The third primary endpoint of time to cardiovascular death or first heart failure hospitalization in patients with transferrin saturation <20% occurred in 22 women in the treatment group compared with 15 in the placebo group (HR 1.21; 95% CI 0.62–2.36, p = 0.58)." (PMID 40740027, 2025). "Predialysis CKD patients with the best combination of transferrin saturation and ferritin have the best prognosis, whereas those with lower transferrin saturation and ferritin or higher transferrin saturation and ferritin have a worse prognosis and more hospitalizations for heart failure." (PMID 38941000, 2024).
heart failure (continued). "In the Ferric Iron in Heart Failure (FERRIC-HF) trial, intravenous iron sucrose was associated with increased transferrin saturation (p < 0.05), serum ferritin (p < 0.01), NYHA functional class (p < 0.01) compared with no treatment but without changes in hemoglobin (Hb ≤ 12.5 g/dL)." (PMID 37374094, 2023). "In the diagnostic work-up of alcoholic cardiomyopathy, the confirmation of alcohol abuse by carbohydrate deficient transferrin (CDT) and increased liver enzymes, and the involvement of the heart by markers of heart failure (e.g., NT-proBNP) and of necrosis (e.g., troponins or CKMb) is mandatory." (PMID 27582365, 2016). "IRONMAN was a randomized trial of IV FDI versus usual care in patients with symptomatic heart failure, left ventricular ejection fraction (LVEF) ≤45%, and transferrin saturation (TSAT) <20% or ferritin <100 μg/L." (PMID 39453738, 2025). "By the end of the six months evaluation period, subjects with iron therapy displayed significant progress in heart failure symptoms, NYHA functional class, NT-pro-BNP level, hemoglobin level, transferrin saturation, and ferritin level." (PMID 35178308, 2022). "Our networks succinctly illustrate the most influential nodes in both types of heart failure; for example, in ICM myocardium, a cluster of ECM proteins such as EFEMP1, LUM, and COL6A2 are highly influential, as is TF in the coagulation cascade." (PMID 32487995, 2020). "Patients who suffered a heart failure during AMI (n = 17) had increased levels of platelet (CD61+)-and monocyte (CD14+)-derived cMPs carrying TF (CD142+) (P<0.0001 and 0.004, respectively)." (PMID 28207887, 2017). "We applied a common definition for the diagnosis of ID to a large panel of patients with cancer, heart failure (HF), inflammatory bowel disease (IBD), and chronic kidney disease (CKD), where ID was defined as serum ferritin concentration <100 μg/L and/or a transferrin saturation (TSAT) index <20%." (PMID 35268014, 2022). "Therefore, it seems that performing HFE genotype screening in heart failure patients has no value, unless they display clear clinical signs of HH, including biochemical markers as elevated serum ferritin, transferrin saturation and in the future possibly also decreased hepcidin levels." (PMID 20670400, 2010). "Compared with survivors, non-survivors had significantly higher creatinine levels, heart failure prevalence, SOFA, CCI, and SAPS II scores, as well as a higher incidence of malignant cancer, while transferrin, TIBC, and hypertension rates were significantly lower." (PMID 41398781, 2025).
pancreatic cancer (35 papers, 2013 to 2024). "It has been proposed that increased TF expression by endothelial cells enhances angiogenesis, and increased TF expression in tumour cells (Meth-A) and human pancreatic tumours was associated with increased VEGF expression." (PMID 36038791, 2022). "Moreover, one study showed that tumor-derived TF-expressing EVs induce DVT and that these EVs cooperate with host TF in order to cause the prothrombotic state in pancreatic cancer." (PMID 36013171, 2022). "Therefore, serum ferritin and transferrin, which reflect the iron level, can be used as potential diagnostic biomarkers for pancreatic cancer detection." (PMID 34503532, 2021). "In pancreatic cancer, tumour growth under hypoxic conditions has also been attributed to hypoxia-induced alternative splicing of tissue factor, resulting in as-TF expression, which activates carbonic anhydrase IX implicated in late-stage pancreatic cancer growth under hypoxic conditions." (PMID 32536347, 2020). "Among the identified proteins, APOA-I and TF were found to be associated to pancreatic cancer." (PMID 27495108, 2016). "Considering the limited number of hepatobiliary and pancreatic cancer patients in our study, large-scale clinical research is required to further verify the prognostic value of prealbumin and transferrin in these populations." (PMID 38438901, 2024). "For example, when DFO and the HIF-1α inhibitor YC1 were formulated into transferrin-decorated liposome nanoparticles and targeted to transferrin receptor-expressing pancreatic cancer xenografts in mice, xenograft tumor regression was observed." (PMID 36980731, 2023). "It has been reported that the formation of TF/VIIa can upregulate u-PAR expression in the human pancreatic cancer cell line, thereby enhancing tumor invasion and metastasis via u-PA/u-PAR pathways." (PMID 37046617, 2023). "One of the most prominent mechanisms in many cancers, particularly in pancreatic cancer, is enhanced activation of the TF coagulation pathway by upregulating TF on the tumor cell surface and releasing TF-bearing MPs (TF-MPs)." (PMID 37046617, 2023). "Ruscogenin enhanced the expression of transferrin and iron transporter, thus increased the concentration of Fe2+ in cells, which induce ferroptosis in pancreatic cancer cells." (PMID 35246010, 2022). "It wasfound that ruscogenin induced ferroptosis by regulating the levelsof transferrin and ferroportin in pancreatic cancer models, indicatingthis compound is a potential lead compound against pancreatic cancer." (PMID 35312315, 2022). "Previously, we reported the changed profile of carbohydrate-deficient transferrin (a sum of the asialo, monosialo and disialo isoforms of transferrin, CDT for short) in pancreatic diseases, including pancreatitis of different etiologies (alcoholic and biliary) and in pancreatic cancers." (PMID 35329964, 2022). "A pancreatic cancer cell line was established from KPC mice and transfected the cells with the mouse TF gene." (PMID 36046842, 2022). "The ADC generated linking the anti-mouse TF antibody to MMAE using a bis-alkylating conjugation method demonstrated significant TGI in orthotopic and subcutaneous pancreatic cancer allografts." (PMID 36046842, 2022). "A small retrospective study found resected pancreatic tumour specimens had high TF expression and a VTE rate of 26.3% compared to 4.5% in patients with low TF expression." (PMID 34064390, 2021). "Furthermore, this association may not be solely related to TF expression in the primary tumors as results have now shown that circulating microparticles carrying TF are 16- to 26-fold higher in pancreatic cancer patients with thrombosis when compared to healthy controls." (PMID 33365273, 2020).
pancreatic cancer (continued). "Overexpression of tissue factor (TF, CD142) has been associated with increased tumour growth, tumour angiogenesis, and metastatic potential in many malignancies, including pancreatic cancer, and soluble TF may also contribute to activation of the coagulation system in pancreatic cancer." (PMID 30225616, 2018). "Furthermore, high transferrin expression is particularly associated with a malignant phenotype in tumours resistant to conventional therapeutics such as human pancreatic cancer;9 therefore, transferrin–antibody conjugated AuNPs could provide novel alternative treatment options." (PMID 26118301, 2015). "In line with these intriguing data, gemcitabine-loaded transferrin-conjugated gold-MNs also greatly enhanced chemosensitivity of PDAC cells and induced effective regression of human pancreatic cancer xenografts in mice by the combination of photothermal- and chemotherapy." (PMID 35214121, 2022). "Relevant studies have found that pancreatic cancer cell death induced by ART is inhibited by deferoxamine (DFO), while increasing the content of transferrin (HTF) increases the degree of cell death, reflecting that ART-induced cell death depends on the level of free iron." (PMID 34503532, 2021). "Among them, positive (i.e., serum amyloid A, ceruloplasmin, complement factors, haptoglobin) and negative acute-phase reactants (i.e., transthyretin, transferrin) were differentially expressed in sera from ovary, lung, liver, and pancreatic cancer patients." (PMID 23401773, 2013). "Therefore, wogonin induces lipid peroxidation by activating TF and TFRC in an iron-dependent manner but also decreases GSH levels in cells by decreases GSH levels in cells via Nrf2-GPX4 pathway, thereby inducing ferroptosis in pancreatic cancer cells." (PMID 36909174, 2023). "Whereas a strong correlation between TF-expressing EVs and VTE was demonstrated in patients with pancreatic cancer, other studies in different cancers failed to arrive at similar associations." (PMID 36013171, 2022).